AQP5 (aquaporin 5)
Diseases named in the same sentence as AQP5 in open-access papers (continued):
Sharing a sentence is not in itself a finding about the gene and the disease.
pancreatic cancer (continued). "Furthermore, our group reported that both AQP3 and AQP5 play a critical role in cancer cell migration in pancreatic cancer where cells silenced for AQP3 and AQP5 and those double-silenced (AQP3/AQP5) exhibited a significant impairment in cell migration." (PMID 39941100, 2025). "Moreover, in human pancreatic cancer cells, the measured AQP5-mediated H2O2 influx rate indicates the presence of a highly efficient peroxiporin activity." (PMID 31277235, 2019). "Finally, we measured the H2O2 influx rate mediated by AQP5 in human pancreatic cancer cells, and revealed its impact on cell migration under oxidative stress." (PMID 31277235, 2019). "Moreover, in human pancreatic cancer cells, the measured AQP5-mediated H2O2 influx rate indicates a highly efficient peroxiporin activity." (PMID 31277235, 2019). "Additionally, AQP5 gene expression may be explored as a clinical biomarker for the diagnosis or prognosis of pancreatic cancer." (PMID 40305202, 2025). "In a previous publication, we investigated the prognostic value of AQP transcripts in the same pancreatic cancer cohort and discussed the correlations found among various AQP isoforms (AQP1, AQP3, AQP5, and AQP9)." (PMID 40305202, 2025). "In vitro experiments using a human pancreatic cancer cell line confirmed that the transcriptional regulation of EMT and MAPK/ERK signaling pathways is influenced by AQP3 and AQP5 expression levels." (PMID 40305202, 2025). "For that, we cultured a pancreatic cancer cell line, BxPC3, that was screened for AQP expression, revealing high levels of AQP3 and AQP5 expression and much lower levels of AQP1 and AQP8." (PMID 40305202, 2025). "To further validate the correlations found, we analyzed publicly available datasets using TNMplot and observed significant correlations between AQP3 and c-Jun (p < 0.01), and AQP5 with EGFR (p = 0.040) and CDH1 (p < 0.01) in pancreatic cancer." (PMID 40305202, 2025). "In fact, both AQP5 and AQP3 showed measurable peroxiporin activity in pancreatic cancer cells, with AQP5 showing higher efficiency than AQP3." (PMID 31277235, 2019). "The relative gene expression levels of AQP1, AQP3, AQP5, and AQP9 were analyzed using real-time quantitative PCR (RT-qPCR) in 24 paired pancreatic tumors and adjacent healthy tissues according to variables such as age, gender, and tumor invasiveness and aggressiveness." (PMID 37761834, 2023).
diabetic nephropathy (10 papers, 2013 to 2025). "Recently, Go and Zhang also reported that an increase in AQP-5 in patients with diabetic nephropathy is independently associated with a reduction in the glomerular filtration rate." (PMID 33663503, 2021). "Upregulated AQP5 mRNA has been found in all of the 17 kidney biopsies from patients with diabetic nephropathy." (PMID 30336596, 2018). "In the patients with diabetic nephropathy, AQP5 colocalizes with AQP2 in the perinuclear region and AQP5 expression is associated with impaired cellular H3 dimethyl K79." (PMID 23326416, 2013). "We also observed upregulated AQP5 and decreased H3m2K79 in kidney biopsies from patients with diabetic nephropathy (DN)." (PMID 23326416, 2013). "A possible hypothesis is that the SWD-induced hyperosmolarity is similar to the hyperosmolar state of patients with diabetic nephropathy, a condition that leads to an overexpression of AQP5." (PMID 36295616, 2022). "Moreover, depletion of DOT1L led to endogenous AQP5 upregulation, but the upregulated AQP5 contribute to polyuria in patients with diabetic nephropathy, suggesting that DOT1L is critical in renal water homeostasis with DN." (PMID 27846294, 2016). "AQP5 is obviously increased in the kidney tissue of DN patients and urine AQP2 and AQP5 have been identified as potential novel biomarkers of diabetic nephropathy with sensitivity, early appearance, and low invasiveness features." (PMID 30654539, 2019). "In the same experiment, using immunofluorescence on human kidney biopsies, it was found that in controls (patients with minimal change disease, MCD), AQP5 was not identifiable, while it was hyper-expressed in patients with diabetic nephropathy." (PMID 36295616, 2022). "Consistently, AQP5 is expressed in none of 15 normal controls, but in all of 17 kidney biopsies from patients with diabetic nephropathy." (PMID 23326416, 2013). "Additional research has examined the quantities of aquaporin 5 (AQP5) and AQP2 exosome-expelled in urine in 35 diabetic patients, indicating that exosomal AQP5 and AQP2 could serve as potential noninvasive biomarkers for the classification of diabetic nephropathy (DN) clinical stages." (PMID 40305328, 2025).
glioma (10 papers, 2017 to 2025). A benign or malignant brain and spinal cord tumor that arises from glial cells (astrocytes, oligodendrocytes, ependymal cells). "The risk of death for glioma patients after diagnosis showed moderate possible associations with transcript levels for AQPs 1, 2, 3, 6, 9 and 11 (HRs ranging from 1.2 to 1.6), but the hazard ratio was almost doubled for patients with AQP5 transcript levels exceeding the median value (HR1.9)." (PMID 32679804, 2020). "Nevertheless, further study for the role of AQP5 on glioblastoma stem cells is still required to fully elucidate that if AQP5 is associated with differentiation of glioma stem cells and whether it could be a potential therapeutic target in glioma." (PMID 28404978, 2017). "By gene silencing, AQP5 was shown to be essential for human glioma cell proliferation, migration and protecting the cells from apoptosis through regulating the EGFR/ERK/p38 MAPK signaling pathway." (PMID 36010640, 2022). "The results showed that AQP5 expression in lower grade glioma (LGG), LUAD, and SKCM was significantly different for the OS of patients, and in LGG, SKCM, and UCEC, it was significantly different for the disease-specific survival (DSS) of patients." (PMID 33343628, 2020). "AQP5 have been found expressed highly in primary human glioma cells compared with normal tissue, this is in accordance with the study that reported AQPs (such as AQP1, AQP5 and AQP8) have been observed in high-grade tumors of various tissues." (PMID 28404978, 2017). "In this study, we investigated the effects of AQP5 gene silencing on the proliferation, migration and apoptosis of U87-MG and U251 glioma cells through regulating EGFR/ERK/p38 MAPK signaling pathway." (PMID 28404978, 2017). "We investigated the effects of aquaporin 5 (AQP5) gene silencing on the proliferation, migration and apoptosis of human glioma cells through regulating the EGFR/ERK/p38MAPK signaling pathway." (PMID 28404978, 2017). "Furthermore, AQP4 plays a key role in the blood-brain barrier destruction in glioma, whereas AQP5 is closely related to glioma-related brain edema." (PMID 37280594, 2023). "Interestingly, in a previous report, AQP5-silenced human glioma cells also depicted an increased cell apoptotic rate comparing to control, corroborating our results." (PMID 35455986, 2022). "In summarize, we demonstrated that AQP5 gene silencing could inhibit the proliferation, reduce the migration and promote the apoptosis of human glioma cells by suppressing EGFR/ERK/p38 MAPK signaling pathway." (PMID 28404978, 2017). "qRT-PCR was applied to examine the mRNA expressions of AQP5 in five human glioma cell lines." (PMID 28404978, 2017). "In this study, we investigated how AQP5 gene silencing might influence the proliferation and apoptosis of human glioma cells and the involvement of the EGFR/extracellular signal-regulated kinase (ERK)/MAPK pathway to provide a new direction for the treatment of glioma." (PMID 28404978, 2017). "Here, we found that siRNA-mediated AQP5 gene silencing inhibited the proliferation of U87-MG, U251 and LN229 glioma cells." (PMID 28404978, 2017). "Our findings have demonstrated that AQP5 gene silencing inhibited the proliferation, suppressed migration and promoted the apoptosis of U87-MG, U251 and LN229 glioma cells, indicating that AQP5 may be a promising target for novel drug development for glioma." (PMID 28404978, 2017). "However, the role of AQP5 gene expression in glioma has not been studied." (PMID 28404978, 2017).
lung adenocarcinoma (10 papers, 2008 to 2026). A carcinoma that arises from the lung and is characterized by the presence of malignant glandular epithelial cells. "Previous studies have reported that silencing the AQP5 gene leads to a 49.4% reduction in water permeability in human lung adenocarcinoma cells." (PMID 39637010, 2024). "The objective of this review article is to present a potential role of AQP5 in the development of lung adenocarcinoma." (PMID 36766810, 2023). "This article presents the pathophysiological role of AQP5 in the biology of lung adenocarcinoma as well as its prognostic value." (PMID 36766810, 2023). "The elucidation of the role of AQP5 in the process of carcinogenesis of lung adenocarcinoma can result in using this protein as a prognostic biomarker, a solution that the up-to-date research results seem to support." (PMID 36766810, 2023). "In the context of lung adenocarcinoma, increased AQP5 assessed by immunohistochemistry in resected tumors was associated with decreased survival." (PMID 35145418, 2022). "In our study, the expression of AQP5 was upregulated in lung adenocarcinoma, and its high expression correlated with better survival outcome." (PMID 29285217, 2017). "Moreover, overexpression of NFAT5 promoted the proliferation and migration of lung adenocarcinoma cells, which coincided with a considerable increase in the expression of AQP5." (PMID 36766810, 2023). "Moreover, inhibiting NFAT5 expression reduces the proliferation and migration of lung adenocarcinoma cells, which is accompanied by suppressing the expression of aquaporin-5 (AQP5), a water transporter depending on the osmotic gradient." (PMID 30873159, 2019). "Additionally, this could be indirect evidence for the connection of the EGFR pathway with AQP5 expression and its influence on the invasive potential of lung adenocarcinoma." (PMID 36766810, 2023). "Interestingly, AQP5 overexpression was observed predominantly in lung adenocarcinomas (p<0.001)." (PMID 18478076, 2008). "The simultaneous upregulation of AQP5 and MUC5AC has also been observed in lung adenocarcinoma cell line." (PMID 29112967, 2017). "In the lung adenocarcinoma cells, the decreased expression of NFAT5 lowers the proliferation and migration of cells, which is accompanied by a considerable decrease in the expression of AQP5." (PMID 36766810, 2023).
cervical cancer (9 papers, 2012 to 2025). A primary or metastatic malignant neoplasm involving the cervix. "There was a favourable correlation between AQP5 and Ki-67 expression levels and involvement of lymph nodes in cervical cancer, which was strongly correlated with AQP5 and Ki-67." (PMID 38336645, 2024).
non-small cell lung carcinoma (9 papers, 2008 to 2023). A group of at least three distinct histological types of lung cancer, including non-small cell squamous cell carcinoma, adenocarcinoma, and large cell carcinoma. "It is confirmed that high expression of AQP5 was associated with tumor growth, invasion and metastasis in non-small cell lung cancer." (PMID 28404978, 2017). "Overexpression of AQP5 has been associated with increased tumor growth, metastasis, and poor prognosis in some cancer types, while its downregulation has been linked to reduced tumor growth and metastasis in non-small cell lung cancer cells." (PMID 37658903, 2023). "The aim of this paper is to present the potential role of AQP5 in the development of non-small cell lung cancer based on a review of research papers, and to promote the knowledge on AQPs among clinicians." (PMID 36766810, 2023). "AQP5 also showed a positive correlation with the tumor-node-metastasis staging of non-small cell lung cancer." (PMID 30555637, 2018). "For instance, lung epithelium is a well known site of AQP5 expression and the expression level of AQP5 seems to be higher in non small cell lung cancer than in normal lung tissue." (PMID 18612408, 2008). "In non-small cell lung cancer tissues, AQP5 has numerous connections to cancer progression." (PMID 30555637, 2018). "Here, we present both molecular and clinical evidence that AQP5 may play a role in the progression of non small cell lung cancer (NSCLC)." (PMID 18478076, 2008). "In human non-small cell lung cancer cells (NSCLCs), AQP5 increased invasiveness; conversely, expression of AQP5 mutant channels lacking membrane targeting signals or the S156 phosphorylation site did not augment invasiveness." (PMID 29922644, 2018). "In a more recent study, phosphorylation of AQP5 was reported in the tissues of human non small cell lung cancer, but not in normal lung tissues." (PMID 18478076, 2008).
lung fibrosis (7 papers, 2013 to 2022). "It was shown that chronic lung injury and lung fibrosis is associated with decreased protein and mRNA expression of AQP-5 in the lung." (PMID 24941004, 2014). "In different lung fibrosis models, a loss of AQP-5 from alveolar epithelial cells has been described, thus indicating AQP-5 as an early injury marker in lung." (PMID 24941004, 2014). "Decreased expression of aquaporin 5 has been reported in pathological conditions such as acute lung injury and lung fibrosis." (PMID 23326473, 2013). "For AQP-5, it could already be shown in animal experiments that the expression decreases in case of an adenovirus infection or lung fibrosis." (PMID 34181078, 2022). "The early loss of aquaporin-5 which can be found in different pulmonary fibrosis models does not implicate a specific pathogenetic role during fibrogenesis." (PMID 24941004, 2014). "The current in vitro PCLS model revealed several differences to experimental animal models of chronic injury, where during the course of disease, for example in pulmonary fibrosis, a number of AEC I specific proteins are strongly diminished: T1α, ICAM-1, aquaporin-5, RAGE and Cav-1." (PMID 25635824, 2015).
acute respiratory distress syndrome (6 papers, 2019 to 2024). Progressive and life-threatening pulmonary distress in the absence of an underlying pulmonary condition, usually following major trauma or surgery. "AQP5 mutations and polymorphisms are associated with palmoplantar keratoderma and with outcomes in patients with acute respiratory distress syndrome." (PMID 33423702, 2021). "In patients suffering from acute respiratory distress syndrome, attributed to bacterial pneumonia, the AA genotype of the AQP5 promoter SNP was associated with aggravated pulmonary inflammation accompanied by a significant increase in neutrophil counts in the bronchoalveolar lavage fluid." (PMID 31867018, 2019). "In this regard, the AQP5 −1364A/C promoter SNP was found to affect neutrophil migration into the lungs and the AA genotypes were associated with aggravated pulmonary inflammation in acute respiratory distress syndrome evoked by bacteria." (PMID 31867018, 2019). "The association between the AQP5 promoter -1364A/C polymorphism and AKI in patients with pneumonia-induced acute respiratory distress syndrome (ARDS) were examined." (PMID 39544938, 2024).
hepatocellular carcinoma (6 papers, 2013 to 2025). A malignant tumor that arises from hepatocytes. "Additionally, microRNA-325-3p, identified as being downregulated in human hepatocellular carcinoma cells and tissues, modulates cell proliferation and apoptosis by directly targeting the tumor suppressor AQP5." (PMID 38379959, 2023). "The correlation of AQP3 and AQP5 with EMT and tumorigenesis has also been reported in triple-negative breast cancer and hepatocellular carcinoma patients, suggesting the potential of AQP3 and AQP5 as prognostic and therapeutic markers." (PMID 39941100, 2025). "addressed the role of miR-325-3p and AQP5 in the proliferation and apoptosis of HBV-infected hepatocellular carcinoma (HCC) cells." (PMID 33898103, 2021). "In hepatocellular carcinoma, miR-124 can decrease AQP3 expression, inhibiting cell proliferation and migration, while miR-1271-5p can prevent hepatitis B-virus-mediated liver cancer growth in vivo by decreasing the expression of AQP5." (PMID 39941100, 2025).
invasive ductal carcinoma (6 papers, 2011 to 2024). "In contrast, in the tissue sections of invasive ductal carcinoma of breast, AQP5 labeling was also associated with invasive tumor cells, in addition to the ductal epithelial cells." (PMID 22145049, 2011). "In contrast, in invasive ductal carcinoma, prominent AQP5 labeling was associated with cancer cells, whereas some ducts were unlabeled and apical polarity of AQP5 in ducts was lost." (PMID 22145049, 2011). "In summary, prominent AQP5 expression was seen in the cancer cells with the loss of polarity of ductal epithelia during the progression of invasive ductal carcinoma of breast." (PMID 22145049, 2011). "Whether AQP5 reduction is causal for morphological changes, or vice versa, is not fully understood, but, in an earlier report, high levels of AQP5 were measured in biopsies of invasive ductal carcinoma of human breast, in which ductal epithelial cells had lost apical polarity." (PMID 25767807, 2015). "AQP5 was mainly expressed at apical domains of ductal epithelial cells in breast benign tumor, while such apical polarity of AQP5 in ducts was lost in invasive ductal carcinoma." (PMID 25886458, 2015). "Importantly, we demonstrated that intense AQP5 labeling was seen in the invasive ductal carcinoma cells in human patients exhibiting LN metastasis." (PMID 22145049, 2011). "More prominent AQP5 labeling was associated with invasive cancer cells, particularly in the invasive ductal carcinoma with lymph node (LN) metastasis, whereas the labeling was weaker in the invasive ductal carcinoma without lymph node metastasis." (PMID 22145049, 2011). "Thus, increased AQP5 expression in the invasive ductal carcinoma of breast could suggest its role in the promotion and cell growth of cancer cells." (PMID 22145049, 2011).
chronic myelogenous leukemia (5 papers, 2008 to 2024). "AQP5 small interfering RNA (siRNA) treated LAMA84 CML cells showed a significant decrease in cellular proliferation when compared to control siRNA administered cells, according to a study on human chronic myelogenous leukaemia (CML)." (PMID 38336645, 2024). "Similarly, overexpression of AQP5 resulted in increased cell proliferation whereas small interfering RNA (siRNA) against AQP5 reduced cell proliferation rate in K562 and LAMA84 chronic myeloid leukemia cells." (PMID 25344048, 2014).